STAT1 (signal transducer and activator of transcription 1)
Diseases named in the same sentence as STAT1 in open-access papers (continued):
Sharing a sentence is not in itself a finding about the gene and the disease.
myocardial infarction (10 papers, 2015 to 2024). Gross necrosis of the myocardium, as a result of interruption of the blood supply to the area, as in coronary thrombosis. "Evidence from in vivo experiments has also shown that STAT1 deficiency in the heart protects against myocardial infarction." (PMID 31171760, 2019). "In this study, we addressed the functional significance of co-operative DNA binding of the cytokine-driven transcription factor STAT1 (signal transducer and activator of transcription 1) in an experimental murine model of acute myocardial infarction (MI)." (PMID 36923955, 2023). "Based on these findings, we hypothesized that STAT1 drives a pro-inflammatory program during myocardial infarction and that loss of STAT1 co-operativity may alter the transcriptional profile toward a cardioprotective pro-survival program during the acute phase of MI within 24 h after surgery." (PMID 36923955, 2023). "In the LAD ligation of a rat model, as early as 5 minutes after myocardial infarction, we observed JAK2, STAT1, STAT3, STAT5a, and STAT6 phosphorylation." (PMID 34516361, 2021). "We found that the treatment of both CAY10576 and fludarabine reversed TRIM6-aggravated myocardial infarct size and serum CPK level, therefore illustrating that TRIM6 promotes MI/R injury by inducing IKKε/STAT1 activation-mediated myocardial apoptosis." (PMID 31171760, 2019). "Taken together, these findings suggested that IFN-β-responsive MICFs recruit monocytes/macrophages after myocardial infarction, and macrophages secreted IFN-β phosphorylate STAT1 in MICFs which further increases the expression of Ccl2, Ccl7, and Ccl12, forming a positive feedback loop." (PMID 38530808, 2024).
rosacea (10 papers, 2021 to 2025). A chronic erythematous skin disorder that affects the face. "A recent study reported that pediatric demodicosis with rosacea-type rash is associated with gain-of-function mutations in STAT1." (PMID 38398439, 2024). "A recent case series also reported that most early-onset rosacea patients showed the gain-of-function mutation in STAT1, suggesting a genetic predisposition to rosacea in early-onset rosacea cases." (PMID 38398439, 2024). "Ultimately, skin barrier dysfunction is implicated in all phenotypes of rosacea and future therapies should target new pathogenic insights such as the roles of STAT1 and STAT3." (PMID 38193038, 2023). "Rosacea-like demodicosis appears as a novel and important clinical phenotype among patients with STAT1 GOF mutation." (PMID 34987506, 2021). "Our findings add more data to the association between rosacea-like demodicosis and STAT1 GOF." (PMID 40881691, 2025). "Familial rosacea associated with a gain-of-function mutation (C324R) in STAT1 suggests that STAT1 could lead to chronic facial inflammation as the cause of rosacea." (PMID 34290700, 2021). "IRF1 regulated the IFNγ/STAT1 signaling pathway in keratinocytes and enhanced their interaction with macrophages, which drove the persistent inflammatory response of rosacea and then induced clinical manifestations such as pustules, papules, and heat pain." (PMID 40635520, 2025). "Recently, STAT1 was discovered to mediate keratinocyte-immune cell crosstalk in the skin with major implications in rosacea pathogenesis as it relates to skin barrier and immune cell activation." (PMID 38193038, 2023). "Epidermal RNA-seq and immunohistochemistry analysis further validated the epithelial-derived STAT1 signature in rosacea lesions." (PMID 34290700, 2021). "Gene ontology, pathway, TF enrichment and immunohistochemistry results suggested that STAT1 was the potential core of the critical TF networks connecting the epithelial–immune crosstalk in rosacea lesions." (PMID 34290700, 2021). "Among the 264 upregulated genes were 12 overlapped TFs in rosacea lesions, including STAT1, FOXE1 and ERG." (PMID 34290700, 2021). "Whether STAT1 has a role in the pathogenesis of rosacea and acne by regulating gene transcription to mediate the immune and inflammatory actions of IFN-γ remains to be confirmed in the future." (PMID 38321132, 2024). "In addition, we identified the critical role of IRF1 and IRF8 in FFA and rosacea and the high expression of STAT1 in this study." (PMID 36091020, 2022). "Our findings provide a new model that diverse inflammatory processes in rosacea may be driven largely by just a small number of hubs within the epidermal transcription circuitry, such as STAT1/IRF1." (PMID 34290700, 2021). "Taken together, we suggest that IFNγ/STAT1 is the core of the critical gene regulatory network connecting the epithelial–immune crosstalk in rosacea development, and targeting IFNγ/STAT1 might be a potential therapy for the treatment of rosacea." (PMID 34290700, 2021). "Rosacea and demodicosis might be underrecognized in STAT1 GOF." (PMID 40881691, 2025). "To confirm whether the STAT1 signature derived from epidermis contributed to rosacea lesions, we used epidermal RNA-seq and identified a gene set overlapping between LS (n=18) versus HS (n=5) and LS (n=18) versus NS (n=18), with 264 genes showing elevated expression in both comparisons." (PMID 34290700, 2021). "The expression of CXCL10, MMP9, IL1B, CXCL8, and CXCR4 were co-regulated by IRF1, STAT1, STAT3, IKBKB, HDAC1, ETS1, and CEBPB, which were highly expressed in rosacea and acne lesions." (PMID 38321132, 2024). "The infiltration of CD4+ T cells and the expression of Stat1, Stat3, and IL-17A were repressed by EGCG treatment in rosacea-like mice." (PMID 36937834, 2023). "And the result of msVIPER analysis in datasets GSE65914 and GSE186075 suggested that STAT1 was activated in both FFA and rosacea (P<0.05)." (PMID 36091020, 2022).
rosacea (continued). "Further verification of the GSE65914 and GSE125733 datasets was performed, and STAT1, which is involved in the regulation of three hub genes (IRF1, IRF8, and CXCL10), was found to be differentially expressed in FFA and rosacea." (PMID 36091020, 2022). "Finally, our findings suggested STAT1 might be a potential therapeutic target for rosacea." (PMID 34290700, 2021). "We further identified common inflammatory signatures, the TF network in whole-skin and epidermis, and epidermal STAT1/IRF1 signature and epithelial–immune crosstalk for rosacea lesions." (PMID 34290700, 2021). "Consistently, by immunohistochemistry we verified the increased nuclear localization of phosphor-STAT1, IRF1 and IRF8 in both epidermis and dermal infiltration of rosacea lesions." (PMID 34290700, 2021). "By immunohistochemistry we also demonstrated that the nuclear localization of phosphor-STAT1 and IRF1 was increased in epidermal cells of rosacea lesions." (PMID 34290700, 2021). "There is an overactive keratinocyte–macrophage crosstalk via the epidermal-derived IFN-γ/STAT1/IRF1 signature in rosacea, which might be an argument for the activation of the innate immune system for rosacea development." (PMID 36091020, 2022). "And further msVIPER analysis confirmed the activation of STAT1 in FFA and rosacea." (PMID 36091020, 2022). "Furthermore, in terms of the effect of STAT1/IRF1 on M1 polarization, our previous study found that ADAMDEC1 plays a pro-inflammatory role in rosacea by modulating the M1 polarization of macrophages." (PMID 34290700, 2021). "Therefore, the IFN-γ/STAT1/IRF1 pathway might regulate M1 polarization in the presence of FFA and rosacea." (PMID 36091020, 2022). "Furthermore, STAT1 and IRF1 were identified across all rosacea subtypes." (PMID 34290700, 2021).
severe combined immunodeficiency (10 papers, 2012 to 2025). Severe combined immunodeficiency (SCID) comprises a group of rare monogenic primary immunodeficiency disorders characterized by a lack of functional peripheral T lymphocytes resulting in early-onset severe respiratory infections and failure to thrive. "Due to the impaired signaling of both IFN-α/β and IFN-γ, patients with biallelic STAT1 deficiency have high morbidity and mortality in the first year of life from infection and inflammatory diseases, making them more comparable to severe combined immunodeficiency (SCID) than other STAT1 defects." (PMID 39599507, 2024). "Diagnoses included common variable immunodeficiency (n=25), specific antibody deficiency (n=9), ataxia-telangiectasia (n=5), X-linked agammaglobulinemia (n=4), PIK3CD-related disorders (n=4), hyper-IgM syndrome (n=4), combined immunodeficiency (n=3), and STAT1 gain-of-function (n=1)." (PMID 40114918, 2025). "Such diseases include CD25 or IL-2RA deficiency, mutations within STAT5b, STAT1 or STAT3, Dedicator of Cytokinesis 8 (DOCK8) deficiency as well as infantile or eosinophilic enteropathies and severe combined immunodeficiency (SCID)." (PMID 35207219, 2022).
thyroid cancer (10 papers, 2019 to 2026). "Collectively, these results established STAT1 as a potent negative regulator of thyroid cancer dedifferentiation and stemness." (PMID 41522349, 2026). "Direct binding of IGF2BP2 to STAT1 mRNA in both PTC and ATC cell lines was confirmed by RIP assay, demonstrating the consistency of the IGF2BP2-STAT1 axis across thyroid cancer subtypes." (PMID 41522349, 2026). "In conclusion, our study elucidates a novel thyroid-specific regulatory axis involving IGF2BP2 and STAT1 that drives dedifferentiation and enhances stemness in diverse subtypes of differentiated thyroid cancers." (PMID 41522349, 2026). "Clinically, high STAT1 mRNA expression correlated with significantly longer overall survival in thyroid cancer patients (P=0.0033)." (PMID 41522349, 2026). "Subsequent functional assays demonstrated STAT1's tumor-suppressive role: STAT1 knockdown promoted, while overexpression inhibited thyroid cancer cell proliferation." (PMID 41522349, 2026). "In this study, prognostic analysis and functional phenotypic experiments across thyroid carcinoma differentiation subtypes revealed a tumor-suppressive role of STAT1." (PMID 41522349, 2026). "Elevated STAT1 expression in tumor tissues correlated positively with adverse clinicopathological features, supporting its role as a potential oncogenic factor in thyroid cancer." (PMID 41208879, 2025). "Upon reviewing the literature, we found that only hsa-miR-515-5p has some relevance in the context of the STAT1 gene, particularly in thyroid cancer, where miR-515-5p was downregulated." (PMID 40407590, 2025). "SIGLEC-15 is indicated as a new immune checkpoint for thyroid cancer since it acts as a putative oncogene, activating the STAT1/STAT3 signaling pathway to promote thyroid cancer cell growth, leading to an increase in immunosuppression." (PMID 38338696, 2024). "The long non-coding RNA transcriptionally mediated by STAT1 regulates thyroid cancer cell growth, migration, and invasion." (PMID 36675746, 2022). "TCGA and GTEx database analysis confirmed STAT1 upregulation in thyroid cancers." (PMID 41208879, 2025). "Then, we respectively silenced and overexpressed STAT1 in two thyroid cancer cells." (PMID 33976749, 2021). "Above results demonstrated that ZFPM2-AS1 could be transcriptionally regulated by STAT1 in thyroid cancer." (PMID 33976749, 2021). "Our data showed that STAT1 expression was raised both in thyroid cancer tissues and cells." (PMID 33976749, 2021). "Similarly, STAT1 acts as a tumor suppressor in thyroid cancer." (PMID 36675746, 2022). "Taken together, our results showed that STAT1 was a dominant contributor responsible for the pro-dedifferentiation and tumor-promoting effects driven by IGF2BP2 in thyroid cancer." (PMID 41522349, 2026). "Mechanistically, ZFPM2-AS1 was transcriptionally regulated by STAT1 and bound to miR-515-5p through competitive competition with TUSC3 in thyroid cancer cells." (PMID 33976749, 2021). "Mechanistically, ZFPM2-AS1 transcriptionally regulated by STAT1, could bind miR-515-5p through competitively competing with TUSC3 in thyroid cancer cells." (PMID 33976749, 2021). "Likewise, the interfered STAT1 expression effectively counteracted the impact of IGF2BP2 inhibition in CAL62 cells, restoring proliferation and validating that STAT1 mediates the function of IGF2BP2 in promoting thyroid cancer dedifferentiation and CSCs features." (PMID 41522349, 2026).
cholangiocarcinoma (9 papers, 2009 to 2024). A carcinoma that arises from the intrahepatic biliary tree (intrahepatic cholangiocarcinoma) or from the junction, or adjacent to the junction, of the right and left hepatic ducts (hilar cholangiocarcinoma). "Among cholangiocarcinoma patient specimens, specimens with higher levels of phosphorylated STAT1 and STAT3 exhibited higher ALDH1A3 expression and vice versa." (PMID 34440089, 2021). "Another promising target uncovered in this report is STAT-1 which was overexpressed nearly 9-fold in cases of cholangiocarcinoma." (PMID 19435499, 2009). "Collectively, our studies suggest that ruxolitinib might suppress the ALDH1A3 activation through the JAK2/STAT1/3 pathway in cholangiocarcinoma, and trials should be undertaken to evaluate its efficacy in clinical therapy." (PMID 34440089, 2021). "Furthermore, EGCG with quercetin can block the JAK/STAT pathway, ultimately making STAT1 and STAT3 inactive in cholangiocarcinoma (CCA) cells." (PMID 36193062, 2022).
chronic granulomatous disease (9 papers, 2018 to 2025). Chronic granulomatous disease (CGD) is a rare primary immunodeficiency, mainly affecting phagocytes, which is characterized by an increased susceptibility to severe and recurrent bacterial and fungal infections, along with the development of granulomas. "Genetic defects in PNP, PIK3CD, STAT1, ISG15, IL2RB, GS3, DNASE2 and genes associating chronic granulomatous disease were found among 7 of the 25 patients who underwent genetical testing." (PMID 35964089, 2022). "For example, the PM2 score was highly elevated in deficiency of adenosine deaminase 2 (DADA2) patients and several PIDs such as STAT1 gain-of-function (STAT1 GOF) and X-linked chronic granulomatous disease (X-CGD), relative to healthy subjects." (PMID 36993430, 2023). "However, there are reports of EoE in patients with IEI, including CVID, chronic granulomatous disease (CGD), and STAT1 gain of function." (PMID 36211419, 2022).
coronary artery disease (9 papers, 2014 to 2025). "STAT1 plays different functions in various pathological states of the heart, such as a protective role in cardiac hypertrophy 31 but a pathogenic role in ischemic heart disease 26, 27, which makes it difficult to be a feasible target for heart diseases." (PMID 39897566, 2025). "Many authors describe a conflicting function of STAT1 and STAT3 in ischemic heart disease where STAT1 contributes to the loss of cardiomyocytes and STAT3 protects them from I/R injury." (PMID 32987855, 2020). "STAT1 belongs to a family of molecules known to be expressed in the heart, and to play a role in the link between coronary artery disease and inflammatory responses in vascular cells." (PMID 30303482, 2018). "Moreover, using data mining of human plaque transcriptomes, expression of a selection of these STAT1-dependent pro-atherogenic genes was found to be increased in coronary artery disease (CAD) and carotid atherosclerosis." (PMID 25478796, 2014). "STAT1 and STAT3 have been shown to play roles in ischemic heart disease, and in our study, we found that a gene in the STAT family (STAT4) was a human-specific DEG." (PMID 34003819, 2021). "Our study indeed provides evidence that in ECs and VSMCs STAT1 coordinates a platform for cross-talk between IFNγ and TLR4, and identifies a STAT1-dependent gene signature that reflects a pro-atherogenic state in coronary artery disease (CAD) and carotid atherosclerosis." (PMID 25478796, 2014).
endothelial dysfunction (9 papers, 2014 to 2025). In vascular diseases, endothelial dysfunction is a systemic pathological state of the endothelium (the inner lining of blood vessels) and can be broadly defined as an imbalance between vasodilating and vasoconstricting substances produced by (or acting on) the endothelium. "Upregulated expression of STAT1 was associated with endothelial dysfunction, and was validated as a molecular marker for maternal and fetal T2D." (PMID 32438712, 2020). "Most importantly, we determined that FABP4 can lead to endothelial dysfunction by ERK/JNK/STAT-1 signaling, eNOS, and SDF-1 pathways." (PMID 33287461, 2020). "In this study, FABP4 could enhance endothelial adhesion and induce endothelial dysfunction by activating ERK/JNK/STAT-1 signaling pathways and inhibiting both eNOS and SDF-1 expression in HCAECs." (PMID 33287461, 2020). "Overall, FABP4 can lead to endothelial dysfunction through different mechanisms, including ERK/ JNK/ STAT-1, eNOS, and SDF-1 signaling pathways." (PMID 33287461, 2020). "Therefore, the predicted binding of STAT1 and KDR may be related to KDR overexpression and endothelial dysfunction in CH, which needs further investigation." (PMID 38650036, 2024).
Granuloma (9 papers, 2014 to 2025). A compact, organized collection of mature mononuclear phagocytes, which may be but is not necessarily accompanied by accessory features such as necrosis. "Other investigators have reported that Stat1−/− mice infected with M. tuberculosis have larger granuloma development compared their infected Stat1+/+ counterparts." (PMID 28716119, 2017). "We observed that rMWCNTs caused more persistent lung inflammation, as well as airway mucous cell metaplasia and larger granulomas compared to tMWCNT exposure in wild type Stat1+/+ mice." (PMID 28716119, 2017). "Similarly, cases of patients with dominant negative STAT1 LOF mutations also document non-necrotic granulomas in the context of mycobacterial infections." (PMID 40755768, 2025). "In pleural biopsies, widespread STAT1 phosphorylation was seen in CD68+ cells, which are generally found in the core of organized granulomas." (PMID 38995971, 2024). "It remains unknown if these mechanisms operate independently or in tandem in granulomas, but results and in vitro studies identifying M1 cells as sources of MMT in biology suggest the STAT1/STAT3 axis is a significant contributor." (PMID 33370784, 2020). "Furthermore, since nuclear localized NF-κB, phospho-STAT-1 and phospho-STAT-6 were detected in granuloma FCMs, activators of the pathways leading to M1 and M2 polarization also existed in adequate quantities in the presence or absence of T or B lymphocytes." (PMID 25389425, 2014). "We then highlighted STAT1/STAT3 simulated macrophages that were not exposed to Mtb in images of simulated granulomas to determine where MMT could occur in different granulomas." (PMID 33370784, 2020). "To assess whether dual STAT1/STAT3+ activated macrophages are present in granulomas, and were they are located, we used IHC to visualize the phosphorylated versions of these proteins in NHP granulomas." (PMID 33370784, 2020).
Hypertension (9 papers, 2019 to 2025). The presence of chronic increased pressure in the systemic arterial system. "By combining fine mapping, massively parallel reporter assays, and gene editing, we identified super enhancers that drive the expression of PRDM6 and are partly regulated by STAT1 as the causal variants for hypertension." (PMID 36602864, 2023). "Interestingly, STAT1 was also significantly upregulated in hypertension-associated HFpEF mice." (PMID 39044275, 2024). "STAT1 has been reported to play a regulatory role in hypertension and chronic kidney disease (CKD)." (PMID 33448153, 2021). "Notably, while the pro-inflammatory role of STAT family members, such as STAT3, in hypertension has been reported, the role of STAT1/STAT2 in endothelial inflammation remains unclear." (PMID 40332339, 2025). "Collectively, these findings indicate that under high-salt DOCA-induced hypertension conditions, IRF5 acts as a key regulatory factor, likely interacting with STAT1 and STAT2 within the same regulatory network, contributing to the pathological processes in SSH." (PMID 40332339, 2025).